MUC4 (mucin 4, cell surface associated)
Diseases named in the same sentence as MUC4 in open-access papers (continued):
Sharing a sentence is not in itself a finding about the gene and the disease.
tumor (continued). "Previous studies indicate that overexpression of the membrane-associated mucin MUC4 is potently anti-adhesive to cultured tumor cells, and suppresses cellular apoptotic response to a variety of insults." (PMID 19761616, 2009). "In pancreatic malignancy, MUC4 is a diagnostic and prognostic tumour marker, whereas MUC5AC has been proposed as a sensitive serological marker for BTC." (PMID 18475301, 2008). "Statistical analysis was conducted to determine the association of MUC4 expression pattern with cancer type, differentiation and stage of the tumour." (PMID 18781152, 2008). "We believe that MUC4 is implicated in tumour growth and metastasis by directly altering the tumour cell properties (adhesion/aggregation and motility), and/or in part, via modulating HER2 expression." (PMID 15494719, 2004). "Specifically, MUC4’s role in enhancing ErbB signaling pathways is linked to creating a microenvironment that promotes the accumulation of immune suppressive cells, thereby hindering effective anti-tumor immunity." (PMID 40655139, 2025). "Muc4 encodes a highly glycosylated protein that constitutes a major component of mucus and may promote tumor growth by repressing apoptosis." (PMID 41294802, 2025). "Additionally, MUC4 has been found to influence the tumor-associated immune response by modulating the recruitment and activity of various immune cell types." (PMID 40655139, 2025). "Cells in the tumor or the microenvironment express membrane-associated mucin 4 (MUC4)." (PMID 40181988, 2025). "MUC4 has been implicated in promoting tumor progression through various mechanisms." (PMID 40909948, 2025). "MUC4 codes for one of the mucins contributing to the protective mucous layer lining the small and large bowel, and its over-expression has been associated with both poorer outcome and enhancement of anti-tumour response." (PMID 38505585, 2024). "MUC4 expression was elevated throughout the epithelial thickness in normal or dysplastic mucosa close to the invasive tumour, indicating a cellular protective function of the mucin in reaction to the tumour and its predisposing environmental factors." (PMID 38929537, 2024). "LGFMS and SEF may appear together as a hybrid tumor, and they share diagnostic features including MUC4 immunoreactivity and FUS gene rearrangements." (PMID 38254244, 2024). "Finally, in our cohort, MUC4 was associated with tumor stage, with stage 4 tumors having significantly higher MUC4 expression than stage 1 tumors." (PMID 37674528, 2023). "The presence of MUC4 in both tumor types may hold diagnostic significance, potentially highlighting a previously uncharacterized molecular aspect of these malignancies." (PMID 38156143, 2023). "Furthermore, MUC4 in breast cancer is associated with circulating tumour cells and with an increase of tumour cell survival in circulation, promoting metastasis." (PMID 35454762, 2022). "Among these, MUC4 as well as MUC5AC are highly tumor-associated in BTC." (PMID 36230626, 2022). "Due to the lack of clinical data in ICGC database, we cannot determine whether MUC4 mutation is also associated with prognosis and tumor immunity in Chinese patients." (PMID 33714943, 2021). "In addition, the existence of MUC4 splice variants, autoantibodies against abnormally glycosylated MUC4 and T‐cell clones against MUC4 mutations strengthen its importance as a tumour‐associated antigen in vaccine research." (PMID 32745356, 2020). "MUC4, regarded as the tumour‐associated mucin of the pancreas, might be a promising biomarker to discriminate PC from pancreatitis." (PMID 32745356, 2020). "However, the diminution of MUC4 expression has been associated with tumour progression and with an increase infiltration of immune CD8+ T and natural killer cells." (PMID 29665859, 2018). "The possible underlying mechanism is that the expression of MUC4 could inhibit apoptosis by the activation of caspase-9, which further resulted in the development of drug resistance in tumor cells." (PMID 26673820, 2016).
tumor (continued). "Furthermore, MUC1 and MUC4 hypomethylation status is statistically associated with development of distant metastasis, tumor stage and overall survival for PDAC (stage IIA and IIB) patients." (PMID 27283771, 2016). "Moreover, the abundant O-linked glycosylation of MUC4 contributes to its anti-adhesive properties, masks antigens on tumor cell surfaces and inhibits cell killing by cytotoxic lymphocytes." (PMID 19761616, 2009). "MUC4 is also often overexpressed in epithelial cancers and our immunohistochemical studies have shown that aberrant expression of MUC4 is associated with invasive proliferation of tumours and a poor outcome for patients." (PMID 19127263, 2009). "Moreover, in this study, VHL represented the predominant group of mutations (50.5%) but significant results were founded only for BAP1 mutation and its association with ill-defined tumor margins and the presence of calcification and for MUC4 mutation and its connection with exophitic growth." (PMID 38666933, 2024). "Thus, gastric MUC4 expression occurs in a variety of tumor sites, may be somewhat more common in samples with active Hp infection, and may be associated with tumor stage in some cohorts." (PMID 37674528, 2023). "The bands show a varied pattern for each of the MUC4+ cell lines; these differences are most likely caused by a small amount of protein degradation or a binding to the various (differentially glycosylated) tumor isoforms that are usually present when MUC4 is expressed on the cell surface." (PMID 30952968, 2019). "In addition, we postulate that the expression of MUC4 in IMPC could be one of the causes of the aggressive behavior of this tumor." (PMID 29281999, 2017). "Interestingly, we observed a significant loss of MUC4 in SSA/P compared to HP, suggesting that loss of MUC4 might play an important role during serrated pathway of neoplasia." (PMID 27705923, 2017). "This complex stimulates the PI3K pathway, thereby enhancing the secretion of MUC4 mucin within tumor cells; MUC4, in turn, activates ErbB2, forming a sustained positive feedback loop involving the ErbB2/ErbB3-MUC4 axis." (PMID 41310663, 2025). "This suggests that MUC4 plays a vital role in promoting an inflammatory microenvironment that is conducive to CSCs generation, thereby supporting tumor malignancy and treatment resistance." (PMID 40655139, 2025). "We sought to determine the ability of F5 to distribute selectively, in vivo, to appropriate tumor tissues, i.e., those that are MUC4+." (PMID 40649822, 2025). "The strong positive expression of MUC4 and Vimentin, along with the elevated Ki67 index, was indicative of high tumor reactivity." (PMID 40144208, 2025). "In this paper, we show how F5 labeled with a near-infrared dye can target MUC4-expressing tumors in mice and is selective for MUC4+ tumor over those that are MUC4−." (PMID 40649822, 2025). "Tumor cells were positive for keratin, S-100 protein, α-smooth muscle actin, and MUC4, and the Ki67 labeling index was about 40%." (PMID 40151688, 2025). "The role of MUC4 in NSCLC tumor cells appears to be limited to apoptosis and the inhibition of differentiation, with no impact on the proliferation of the cells." (PMID 40655139, 2025). "MUC4 has gained increasing recognition for its involvement in tumor progression and immune evasion mechanisms." (PMID 40655139, 2025). "Strong MUC4 staining in collected tumors and negligible MUC4 staining in normal organs further strengthen the validity of using anti-MUC4-IR800 for tumor labeling." (PMID 40563681, 2025). "Meanwhile, MUC4 is a ubiquitous player in multiple tumor types, including pancreatic, lung, and endometrial cancers." (PMID 40655139, 2025).
tumor (continued). "These MUC4-induced signaling pathways were found to protect tumor cells from HER2-targeted therapy in studies of cancer treatments." (PMID 40699805, 2025). "The expression of MUC1 and MUC4 membrane-bound mucins was detected in the cytoplasm (97% and 54% of all tumours, respectively) and in the apical membrane (91% and 60% of all tumours, respectively)." (PMID 39966658, 2025). "Studies have indicated a correlation between MUC4 expression and the degree of differentiation, tumor stage, and ErbB2 expression in NSCLC." (PMID 40655139, 2025). "Its dual role in promoting tumor growth while also impacting immune response underscores the necessity for further research in this area, to elucidate the mechanisms through which MUC4 can be effectively targeted for cancer therapy." (PMID 40655139, 2025). "The MUC4 gene, which promotes tumor progression in pancreatic tumors, was downregulated by miR-150 administration, significantly suppressing the growth of tumor cells." (PMID 40872479, 2025). "Theses 13 genes (e.g., COL1A1, POSTN, ASPN, PDGFRA, MUC4, SPARC), implicated notably in EMT and cancer progression, were found to be highly expressed in depth of tumor ID15 and ID08, near the invasive margin." (PMID 40076457, 2025). "The expression of MUC4 also seems to corelate with pre-malignant disease stages (pancreatic intraepithelial neoplasms, PanIN lesions) and increases as tumor aggressiveness increases." (PMID 40649822, 2025). "As far as we know, this is the first instance of a mAb raised to a glycosylated TR sequence from MUC4 to be analyzed for tumor-targeting in a live animal system." (PMID 40649822, 2025). "We recently developed a new mAb that binds MUC4+ tumor cells based on the results of a vaccination study performed with several “random” glycopeptides derived from the TR region of MUC4." (PMID 40649822, 2025). "One case was MUC4 positive in 55% of tumor cells, showing mostly weak to moderate intensity of staining." (PMID 39592485, 2025). "The high expression of Mucin 4 (MUC4), a highly glycosylated membrane-bound protein, promotes tumor cell metastasis and tumor cell resistance to chemotherapy." (PMID 38396476, 2024). "MUC1 and MUC4, which were highly expressed on the surface of tumor cells, were also downregulated in the P. gingivalis‐treated group." (PMID 37666495, 2024). "Fifth, distinguishing FET::CREB fusion neoplasms reported herein from other well-defined EWSR1 fusion entities in the morphological spectrum of SEF-like neoplasms requires more than MUC4 immunohistochemistry and EWSR1 FISH testing." (PMID 39031200, 2024). "In our study, we investigated the tumor mutation landscape between the two subgroups and noted the top four mutated genes: TTN, PIK3CA, KMT2C, and MUC4." (PMID 38672263, 2024). "As a membrane-bound mucin, MUC4 is ordinarily expressed in the trachea, salivary glands, colon, reproductive tract, and bronchioles, and its aberration leads to tumor growth, metastasis, and chemoresistance." (PMID 39338204, 2024). "We observed that MUC4 is a common cancer-related gene between tissue tumor and fresh PDC, with different dbSNP IDs." (PMID 38744935, 2024). "MUC-4 is a novel tumor antigen that significantly contributes to PC development, which is absent in the normal pancreas, making it a highly attractive candidate for immunotherapy and vaccine development." (PMID 38776309, 2024). "All five tumor cases showed single nucleotide variations (SNVs) in MUC4, and four cases showed SNVs in MUC16, both of which were membrane-bound mucins." (PMID 37771441, 2023). "EpCAM is a widely used marker for epithelial cells and tumor cells, and MUC4 is commonly known to be expressed in early PanIN cells." (PMID 37964407, 2023).
tumor (continued). "MUC4 was reported to contribute to cancer progression by suppressing apoptosis and prompting tumor cell proliferation." (PMID 37465449, 2023). "Of note, similarly to MSLN, MUC4 was recently considered as a valuable tumor-related target for immunotherapy and a potential candidate vaccine for PDAC, thanks to its selective expression on PDAC cells." (PMID 37760554, 2023). "MUC4 has also been proved to be a biomarker for pancreatic cancer and drives cell tumor proliferation and invasion in PDAC." (PMID 37284199, 2023). "Similar to our cases, the tumor cells were diffusely positive for MUC4 and GATA3, while exhibiting focal S100 and panTrk staining." (PMID 37415052, 2023). "We also used specific tumor markers to identify the organoids derived from specific subtypes of SGTs, e.g. MUC4 was used to identify MEC, DOG1 and SOX10 were used to identify AciCC, and HER2 and AR were applied to identify SDC." (PMID 36527158, 2022). "MUC4 was expressed homogeneously within the entire tumor parenchyma, mostly in the tumor cell cytoplasm, with less restricted localization than MMP9." (PMID 36400876, 2022). "Only six genes were present in both tumor initiation and tumor evolution stage: MUC4, MUC16, USP6, BCLAF1, KMT2C, and NOTCH2." (PMID 34918496, 2022). "We conclude that the presence of Muc4 is essential for intestinal homeostasis, reduces tumor burden, and improves overall survival." (PMID 35255004, 2022). "The squamoid cells (CK5+, CK8+) and the mucin-producing cells (CK8+, AQP5+, MUC4+) comprised the tumor mass in both PDOs and the parental tumors, and these cells formed typical luminal structure and nest patterns." (PMID 36527158, 2022). "So far, the following targets have been investigated- imaging tumour vasculature, tumour epithelial cells, plectin 1, receptor tyrosine kinase axl, bombesin receptors and MUC4 MRI approach." (PMID 35626142, 2022). "Tumor cells overexpress MUC1 and MUC4 on the surface, both of which exhibit altered glycosylation, potentially representing tumor-specific targets." (PMID 36291752, 2022). "MUC4 is a membrane glycoprotein, it is overexpressed in several cancers and promotes tumor formation, tumor aggressiveness, and poor outcomes in various types of epithelial carcinomas, including ovarian cancer." (PMID 34850406, 2022). "Among the four mutated genes (i.e., NCOR1, MUC16, MUC4, and RSPO2), NCOR1, MUC16, and MUC4 were reported to have been directly involved in modulating tumor microenvironment and thereby mediating drug resistance." (PMID 33504001, 2021). "MUC4 is also known to be involved in the interaction between the tumor cells and surrounding environment." (PMID 34522225, 2021). "Upregulation of MUC1 and MUC4 was also identified in uninvolved colon in IBD, and changes in glycosylation of MUC1 have been implicated in IBD-associated neoplasia." (PMID 34333236, 2021). "There were more poor prognostic deletions in the tumor characterization functional category (e.g., MUC4 and PTPRN2 gene deletions) and better prognostic deletions in the lymphocyte regulation functional category." (PMID 33431054, 2021). "Overexpression of MUC4 not only can promote tumor cells proliferation and invasion, but also protect cells from lymphokine attack." (PMID 33718192, 2021). "Given the distinctive roles of MUC4 in immunomodulation during cancer progression and metastasis, we used TIMER2.0 to investigate the impact of the expression of MUC4 on tumor immune infiltration levels." (PMID 34336844, 2021). "Mucin4 (MUC4), MUC5AC and bile globular membrane (BGM) are highly specific tumor-associated proteins, which are two carrier proteins of CA19–9 in bile tract." (PMID 33962560, 2021).
tumor (continued). "Other markers for airway epithelial cells that are expressed through ALIw5 include the cell surface‐associated mucin MUC4, the gel‐forming mucin MUC5B, and the basal cell progenitor marker tumour protein p63 (TP63) (see GEO GSE136859, CompletePath_Counts.csv)." (PMID 32692488, 2020). "MUC4 can modulate cell apoptosis, regulate cell–cell adhesion and serve as a tumor marker or target for cancer therapy, most of which occurs through modulation of Erb family member signalling." (PMID 32194962, 2020). "One of the underlying mechanisms is epitope masking by components of the tumor microenvironment (TME) such as the MUC4 (mucin 4) or the CD44/Hyaluronan complex." (PMID 32033208, 2020). "DOG1 stain showed moderate dense immunoreactivity, while MUC4 immunostain demonstrated diffuse and strong positivity in the tumor cell cytoplasm." (PMID 32164724, 2020). "In contrast, elevated serum BAs levels increase MUC4 expression in PC, that presumably accelerates tumour progression." (PMID 33328627, 2020). "Among them, MUC1 and MUC4 have been extensively demonstrated to be oncomucins promoting tumor aggressiveness, proliferation, and metastasis, suggesting the potential use of their expression and methylation status as independent prognosis markers." (PMID 33182511, 2020). "On the other hand, TNFα also upregulates pro-metastatic factors, such as MMPs and MUC4, and enhances tumor dissemination." (PMID 32391269, 2020). "In pancreatic cancer, MUC4 expression is increased, especially throughout the stages of tumor development leading to carcinoma." (PMID 27829225, 2017). "MUC4 also facilitates cellular adhesion and subsequent binding to the endothelium and activates immunosuppressive responses to tumor cells." (PMID 27829225, 2017). "MUC4 is overexpressed in 30–95% of all types of BC as well as lymph nodes metastases and tumor vascular emboli." (PMID 28915583, 2017). "These miRNAs are known tumor suppressors that alter activity of many genes involved in tumorigenesis including TGFβR1, MUC4, ARHGAP, and RAB14." (PMID 29137392, 2017). "Epithelial invasion is triggered by the anti-adhesive activities of MUC4, which leads to the disassociation of tumor cells from the primary tumor site." (PMID 27829225, 2017). "Overexpression of MUC4 in human tumor cells promotes anti-adhesive functions and represses the anti-tumor functions of the immune system." (PMID 27829225, 2017). "These MUC4 functions are exploited by various carcinomas to promote the propagation and survival of tumor cells." (PMID 27829225, 2017). "The anti-recognition activity of MUC4 promotes tumor growth by enabling the evasion of both immune surveillance and apoptosis suppression." (PMID 27829225, 2017). "MUC4 protein is thought to contribute to tumor metastasis by limiting the adhesion of tumor cells to primary tumor sites." (PMID 29259192, 2017). "These MUC4-induced pathways play a critical role in cell growth, proliferation, disruption of tight junctions and adherens junctions, tumor progression, and blocking apoptosis." (PMID 28978023, 2017). "These events are facilitated by the sialyl-oligosaccharides on MUC4 and ultimately result in tumor cell invasion and endothelial transmigration." (PMID 27829225, 2017). "Metastasis is induced by MUC4, which triggers the dissociation of tumor cells from the primary tumor site by blocking surface adhesion molecule binding, integrin-mediated cell adhesion, and homotypic cell-cell interactions." (PMID 27829225, 2017). "The AMOP domain had an important role in MUC4/Y (MUC4)-mediated tumour angiogenesis and metastasis of PC cells; and the NOTCH3 signaling was involved." (PMID 27287498, 2016). "Patients with low expression of MUC4 or MUC20 would have a good tumor regression and fewer residual cancer cells." (PMID 26673820, 2016).